NLRP3 (NLR family pyrin domain containing 3)
Diseases named in the same sentence as NLRP3 in open-access papers (continued):
Sharing a sentence is not in itself a finding about the gene and the disease.
glioma (continued). "The NOD-like receptor protein-3 (NLRP3) inflammasome, excessively activated in various cancers including glioma, and its suppression has been shown to reduce tumor growth and prolong survival in glioma-bearing mice." (PMID 38461458, 2024). "In the context of glioma, suppressing NLRP3 led to a decrease in glioma cell growth and invasion." (PMID 38347045, 2024). "Studies have shown that in primary glioma models (U251 and SHG-44), XHP treatment alone downregulated POU4F1 and STAT3 levels and increased LDH release and IL-1β and IL-18 levels, and the apoptosis-associated factor NLRP3 was activated." (PMID 38957318, 2024). "In addition to the previous work, studies to build basic knowledge on NLRP3 inflammasome-targeted therapeutic approaches in gliomas have been performed in parallel." (PMID 37723542, 2023). "The simultaneous physiological, etiological, and therapeutic approaches targeting the NLRP3 inflammasome in glioma have led to remarkable progress, and efforts are being made to fully understand the role of the NLRP3 inflammasome through a translational study based on previous studies." (PMID 37723542, 2023). "Since 2014, the function of the NLRP3 inflammasome in gliomas has been closely investigated." (PMID 37723542, 2023). "Recent research showed that the knockdown of NLRP3 could inhibit the growth and invasion of glioma cells, along with the decrease of IL-1β and NF-κB, indicating a positive correlation between NLRP3 and NF-κB." (PMID 36401196, 2022). "Further research into the interactions between S100A8/S100A9, NLRP3, and common inflammatory cytokines may provide potential therapeutic targets for gliomas." (PMID 34975408, 2021). "In addition, glioma cells display aberrant expression of IL-1β, and NLRP3 seems to contribute to radiotherapy resistance." (PMID 34064909, 2021). "LYZ is marked as the aging-related gene which is controlled by NLRP3 in glioma progression." (PMID 33193654, 2020). "Inhibition of NLRP3 suppresses the proliferation, migration and invasion, and promotes apoptosis in glioma cells, while in contrast, increased expression of NLRP3 significantly enhances the proliferation, migration and invasion as well as attenuating apoptosis in glioma cells." (PMID 33613533, 2020). "NLRP3 inhibition in glioma cells reduces cellular senescence and suppresses tumor growth." (PMID 31727865, 2019). "Moreover, the NLRC4 and NLRP3 inflammasomes were also found to play a role in glioma that is a tumor of the central nervous system." (PMID 31892810, 2019). "NLRC4 and NLRP3 were detected by immunostaining in the brains of glioma patients." (PMID 31133717, 2019). "In an experimental model of glioblastoma, preventing NLRP3 expression decreased cancer development and enhanced survival rate in the mice undergo ionizing radiation (IR) therapy, with NLRP3 being a bridge between brain ageing/glioma development and IR therapy." (PMID 30447690, 2018). "And the role of NLRP3 inflammasome in glioma has also been described." (PMID 27652274, 2016). "Furthermore, NLRP3 activation in gliomas has context-dependent effects." (PMID 41463173, 2025). "Inhibition of NLRP3 and NF-κB p65 could inhibit the growth and invasion of glioma cells." (PMID 34239588, 2021). "Therefore, reducing NLRP3 gene expression may be a future therapeutic target for gliomas though further clarification of the molecular mechanisms is needed." (PMID 30447690, 2018). "The NLRP3 gene signature may serve as a promising biomarker in glioma patients." (PMID 27652274, 2016). "Beyond cytokine signaling, glioma responses involve apoptosis, autophagy, ferroptosis, and mitochondrial stress programs that interface with NF-κB/COX-2/NLRP3 pathways." (PMID 41463173, 2025). "Many of these molecules seem to converge on the same inflammatory pathways that are aberrant in glioma, which include the activation of NF-κB, COX-2, and NLRP3, providing a mechanistic basis for potential chemopreventive and adjunct therapeutic roles." (PMID 41463173, 2025).
glioma (continued). "Recent findings regarding the NLRP3 inflammasome regulatory mechanism have revealed that NLRP3 can trigger the PTEN/AKT and epithelial mesenchymal transition signaling pathways, which in turn induce glioma development, cell death, and spread." (PMID 41157253, 2025). "Pyroptosis offers novel therapeutic strategies, such as targeting GSDMD, NLRP3, or ncRNAs like miR-214 and circWEE1, to enhance TMZ sensitivity, overcome resistance, and curb glioma progression." (PMID 41291696, 2025). "As with other tumors or autoimmune diseases, various inflammasomes, including NLRP3 and NLRC4, have been reported in glioma." (PMID 37723542, 2023). "NLRP6, which shows robust expression in gliomas, also belongs to the NLR family, similar to NLRP3 and NLRC4." (PMID 37723542, 2023). "Emerging evidence regarding the regulatory mechanism of the NLRP3 inflammasome has shown that NLRP3 can induce the EMT and PTEN/AKT signaling pathways and lead to glioma cell proliferation, apoptosis, and metastasis." (PMID 37723542, 2023). "Activation of NLRC4 and NLRP3 inflammasomes in microglia and astrocytes, as well as the upregulation of IRF3 and IRF7, contribute to the poor prognosis of glioma." (PMID 38002346, 2023). "Hyperactivation of NLRP3-AKT axis, and its IL-1β/NF-kB p65 downstream pathway, has been detected in glioma cells and held responsible for cancer proliferation and migration." (PMID 37891577, 2023). "Analysis of tumor protein expression revealed a significantly positive correlation between NLRP3 levels and WHO glioma grade." (PMID 34975408, 2021). "On the other hand, the increase of NLRP3, ASC, caspase-1, and IL-1β proteins in human glioma tissues is significantly correlated with higher World Health Organization grades." (PMID 33613533, 2020). "Unanimously, inhibition of the NLRP3 inflammasome pathway has been suggested to be a promising approach for decreasing tumor cell invasion and survival in HNSC and glioma." (PMID 33613533, 2020). "The results of this study reveal that NLRP3 and NLRC4 inflammasomes are expressed and activated in gliomas and that high expression of NLRC4 in particular is associated with poor overall survival." (PMID 31133717, 2019). "In regard to glioma, several small molecules and drugs, such as galangin (through caspase-3/GSDME axis), benzimidazole (through NF-kB/NLRP3/GSDMD axis), kaempferol (through GSDME and ROS), and AT7519 (through caspase-3 cleavage of GSDME) have shown the capability of inducing pyroptosis." (PMID 41291696, 2025). "Furthermore, we found that calycosin inhibited proliferation, migration, and invasion in U87 and U251 glioma cells, and decreased CXCL10 expression in a dose-dependent manner, along with its downstream effectors such as NLRP3, NF-κB, and IL-1β." (PMID 38461458, 2024). "BHB has also been shown to inhibit glioma cell migration by inhibiting the NLRP3 inflammasome, suggesting that BHB may reduce the inflammatory microenvironment, providing an ancillary therapeutic benefit to the intervention of gliomas." (PMID 36432618, 2022). "Activation of NLRP3 expression by S100A8/S100A9 inhuman PBMCs increased the secretion of pro-inflammatory cytokines (IL-6, IL-1β, TNFα) and chemokines (IL-8, Gro-α, MIP-1α/β) that are prevalent in gliomas." (PMID 34975408, 2021). "Kaplan-Meier survival plots indicated that glioma patients with high NLRC4 expression had a significantly lower overall survival than those with low NLRC4 expression, whereas the expression of NLRP3 did not have a significant association with overall survival." (PMID 31133717, 2019). "Within this review, we discuss the interplay of natural anti-inflammatory compounds with three core inflammatory compounds in glioma, namely, NF-κB, COX-2, and NLRP3, and how these interactions might reprogram the TME to reduce gliomagenesis, immunosuppression, and invasion." (PMID 41463173, 2025).
glioma (continued). "Importantly, a report on the upstream signaling pathway of the NLRP3 inflammasome in gliomas has been published, and activation of the ERK-dependent NF-κB has been shown to activate the NLRP3 inflammasome mediated by vimentin in EV-71-infected glioma." (PMID 37723542, 2023). "Additionally, DNA methylation analysis demonstrated that the promoter methylation levels of AIM2, CASP1, CASP8, NLRP3, and ZBP1 are significantly lower in gliomas than in non-tumor brain tissues." (PMID 39901195, 2025).
hyperlipidemia (48 papers, 2016 to 2026). "To explore the critical role of NLRP3 inflammasome in hyperlipidemia-induced relaxant function loss, we inhibited NLRP3 in ApoE-/- mice through MCC950 treating." (PMID 38992615, 2024). "The NOD-like receptor family pyrin domain-containing 3 (NLRP3) inflammasome is implicated in vascular dysfunction associated with hyperlipidemia-induced vascular injury." (PMID 38992615, 2024). "Pyroptosis induction is closely associated with the activation of the NLRP3 inflammasome, which has been linked to key cardiovascular risk factors, including hyperlipidemia." (PMID 33178827, 2020). "Also, NLRP3 increased activity in the endothelium synergizes with hyperlipidemia to cause a topographic distribution of atherosclerotic lesions." (PMID 31700106, 2019). "The current study provides partial insights into the potential mechanisms through which hyperlipidemia activates the NLRP3 inflammasome, contributing to the impairment of vascular elastic function." (PMID 38992615, 2024). "Hyperlipidemia plays significant roles in promoting TI, and Western diet triggers canonical inflammasome NLRP3-dependent innate immune reprogramming." (PMID 39024553, 2024). "Subsequently, immunofluorescence analysis and immunohistochemical staining revealed that the expression of NLRP3 was significantly upregulated in the kidneys of CKD patients with hyperlipidemia." (PMID 38720901, 2024). "Taken together, our results demonstrate that the Nrf2/ARE signaling pathway attenuates hyperlipidemia-induced renal injury through its antioxidative and anti-inflammatory effects through the downregulation of mtROS-mediated NLRP3 inflammasome activation." (PMID 38720901, 2024). "Recent studies have revealed that the activation of the NOD-like receptor family pyrin domain-containing 3 (NLRP3) inflammasome plays a pivotal role in vascular damage induced by hyperlipidemia." (PMID 38992615, 2024). "It has been reported that the NLRP3 inflammasome is activated in response to sterile stimuli such as hyperglycemia, hyperlipidemia, angiotensin II, and aldosterone in renal tubular epithelial cells." (PMID 38720901, 2024). "Here we demonstrated that Nrf2/ARE antioxidant signaling plays a key role in the activation of the NLRP3 inflammasome in hyperlipidemia-induced renal injury." (PMID 38720901, 2024). "In this study, we aimed to explore the role of the Nrf2/ARE signaling pathway and its regulation of mitochondrial ROS production and NLRP3 inflammasome activation in hyperlipidemia-induced renal tubular epithelial cell injury." (PMID 38720901, 2024). "The expressions of NLRP3 and IL-1β were significantly increased in obese models with hyperlipidemia compared to those with normal lipids." (PMID 36557935, 2022). "In this study, swimming, as a treatment, reduced the expression of NLRP3, caspase-1, and IL-18, thereby indicating that exercise can act as a protective agent against hyperlipidemia-induced neuronal injury." (PMID 34409103, 2021). "In summary, Rg1 improves renal function in DN rats by inhibiting hyperlipidemia-induced pyroptosis in podocytes via targeting mTOR/NF-κB/NLRP3 signaling." (PMID 33133213, 2020). "Hyperlipidemia results in the upregulation of NLRP3, caspase-1, and IL-1β, and leads to pyroptosis in ECs." (PMID 33339328, 2020). "Ginsenoside Rg1 protects podocytes from hyperlipidemia-induced damage by inhibiting pyroptosis through the mTOR/NF-κB/NLRP3 axis, indicating a potential therapeutic function in DN." (PMID 33133213, 2020). "The NLRP3 inflammasome is considered a key factor for the development of NASH induced by hyperlipidemia." (PMID 29849583, 2018). "Next, we detected the expression of NLRP3 in the kidney tissue of CKD patients with hyperlipidemia." (PMID 38720901, 2024).
hyperlipidemia (continued). "Nuclear factor erythroid 2-related factor 2 (Nrf2) is a transcription factor that modulates the cellular redox balance; however, the exact role of Nrf2 signaling and its regulation of the NLRP3 inflammasome in hyperlipidemia-induced kidney injury are poorly understood." (PMID 38720901, 2024). "Therefore, NLRP3 inflammasome plays a crucial role in hyperlipidemia-induced vascular damage, particularly in the progression of atherosclerosis and vascular wall stiffness." (PMID 38992615, 2024). "More importantly, a recent study has reported that paeonol may attenuate NLRP3 mediated inflammation in a hyperlipidemia rat model." (PMID 35303801, 2022). "The NLRP3 inflammasome was also activated in the obese population with hyperlipidemia." (PMID 36557935, 2022). "In addition, Rg1 also inhibited hyperlipidemia-induced NLRP3 inflammasome in the podocytes, which was abrogated by the mTOR activator L-leucine (LEU)." (PMID 33133213, 2020). "In addition, the Nrf2/ARE signaling pathway is activated in renal tubular epithelial cells under hyperlipidemia conditions both in vivo and in vitro, and Nrf2 silencing accelerated palmitic acid (PA)-induced mtROS production, mitochondrial injury, and NLRP3 inflammasome activation." (PMID 38720901, 2024). "However, in hyperlipidemia, the role and mechanisms by which the NLRP3 inflammasome mediates impairment of vascular elastic function remain unclear." (PMID 38992615, 2024). "Thus, targeting the mechanism preserving the mitochondrial redox balance and thereby inhibiting NLRP3 inflammasome activation in CKD patients with hyperlipidemia may be an attractive therapeutic approach." (PMID 38720901, 2024). "Furthermore, hyperlipidemia may induce NLRP3 inflammasome activation in immune cells and produce large amounts of IL-1β, leading to phenotype transformation of VSMCs and synthesis and secretion of MMPs stimulated by IL-1β produced after immune cell infiltration." (PMID 38992615, 2024). "Hyperlipidemia, SYK, and NLRP3 inflammasome are independently critical factors in various vascular injuries, but the relationship among them lacks relevant research at present." (PMID 38992615, 2024). "In summary, we demonstrated that hyperlipidemia induced Nrf2/ARE signaling activation, mitochondrial ROS production, and NLRP3 inflammasome activation." (PMID 38720901, 2024). "Our data confirmed that increased hyperlipidemia-mediated inflammation activated HMGB1-TLR4 signaling, NLRP3 inflammasome formation, and upregulation of pyroptosis markers caspase-1, IL-1β, IL-18, and the pyroptosis executor GSDMD." (PMID 36829889, 2023). "Similarly, paeonol interacts with NLRP3 inflammasomes in a hyperlipidemic rat model has revealed that paeonol can reduce the levels of NLRP3, active caspase 1, and ASC to alleviate rat hyperlipidemia." (PMID 35303801, 2022). "Furthermore, the inhibitory effects of Rg1 on the activation of NLRP3 were reversed by LEU, which strongly suggested that Rg1 decreased hyperlipidemia-induced pyroptosis in podocytes by inhibiting the mTOR/NF-κB/NLRP3 axis." (PMID 33133213, 2020). "Since hyperlipidemia can activate multiple inflammasomes, we knocked down NLRP3 in podocytes and found that absence of NLRP3 inhibited pyroptosis, indicating that it initiates pyroptosis in podocytes during DN." (PMID 33133213, 2020). "MG induced Nrf2/HO-1 signaling, diminished Tylo-induced hyperlipidemia, oxidative stress, IL-1β as well as TNF-α and IL-6 that might arise from the suppression of NLRP3 inflammasome." (PMID 32992548, 2020). "However, the exact mechanism of NLRP3 inflammasome activation in hyperlipidemia-induced kidney injury has not yet been defined." (PMID 38720901, 2024). "Mechanistically, hyperlipidemia induced by HFD feeding acts as the first stimulation for TI via lysoPC stimulation, oxidized low-density lipoprotein (oxLDL) binding to CD36, TLR4 /TLR2 and nucleotide-binding domain, leucine-rich-containing family, pyrin domain-containing 3 (NLRP3) inflammasomes." (PMID 34859106, 2021).
hyperlipidemia (continued). "Moreover, HLF could significantly reduce the levels of NLRP3, caspase-1, IL-1β, IL-6, IL-18, and TNF-α and increase the activities of plasma SOD, CAT, and GSH-PX, which suggested that HLF could effectively relieve the inflammatory response and oxidative stress induced by hyperlipidemia." (PMID 36425260, 2022).